VHL (von Hippel-Lindau tumor suppressor)
Diseases named in the same sentence as VHL in open-access papers (continued):
Sharing a sentence is not in itself a finding about the gene and the disease.
pancreatic neuroendocrine tumor (40 papers, 2009 to 2026). Pancreatic endocrine tumor, also known as pancreatic neuroendocrine tumor (PNET), describes a group of endocrine tumors originating in the pancreas that are usually indolent and benign, but may have the potential to be malignant. "The hypoxia signaling pathway offers therapeutic targets as well, and the HIF inhibitor belzutifan has recently been approved by the FDA for patients with upstream VHL (von Hippo-Lindau) mutations who have pancreatic neuroendocrine tumors." (PMID 37296897, 2023). "Lipid accumulation has been described in other VHL-associated tumors, such as pancreatic neuroendocrine tumors." (PMID 31673890, 2020). "Although VHL mutation is rare in sporadic pancreatic NETs, its inactivation is a significant pathway in the development of sporadic pancreatic NETs." (PMID 33066332, 2020). "Other genetic aberrations found upon mutational analysis include the VHL gene in pancreatic neuroendocrine tumors (NETs) and JAK3, NRAS, RB1, and VHL1 in pulmonary NETs." (PMID 30250431, 2018). "Tumors with mutations in VHL likely represent a distinct group of pancreatic NETs." (PMID 39456803, 2024). "Notably, given the high objective response rates observed in VHL patients with pancreatic NETs, and the known angiogenic signaling implicated in sporadic NETs, a cohort of patients with sporadic advanced pancreatic NETs was also included." (PMID 36358730, 2022). "Although VHL-associated pancreatic NETs may be asymptomatic, they may cause certain obstructive symptoms by blocking the common bile and pancreatic ducts." (PMID 24959293, 2014). "Accordingly, the prognosis of pancreatic NET associated with VHL is considered to be favorable." (PMID 24959293, 2014). "However, in patients with VHL-associated pancreatic NET, surgical treatment must be selected carefully as this type of tumor is rarely the direct cause of mortality." (PMID 24959293, 2014). "Type II, which includes pancreatic pheochromocytoma and islet cell tumors in addition to retinal and CNS angioblastomas, has a higher risk of PHEO and is characterized by VHL missense mutations, resulting in only single amino acid changes in VHL protein." (PMID 40989257, 2025). "We aimed to compare the characteristics of patients with VHL-related pancreatic neuroendocrine tumor (vPNET) meeting either the clinical Danish criteria only (DOC) or IC to those with sporadic PNET (sPNET)." (PMID 36980542, 2023). "On the other hand, mutations in the von Hippel–Lindau (VHL) gene are associated with SCNs, and mutations in the multiple endocrine neoplasia 1 (MEN1) gene or loss of heterozygosity (LOH) are associated with pancreatic neuroendocrine tumors." (PMID 36832193, 2023). "Here we report co-occurrence of germline pathogenic variants in both VHL and SDHA genes in a patient who presented with pancreatic neuroendocrine tumor." (PMID 35875079, 2022). "Twenty-two patients had spRCC, and 22 patients had VHL-associated tumors, including bilateral RCC (45.5% of patients), unilateral RCC (22.7%), CNS hemangioblastoma (86.4%), retinal hemangioma (59.1%), and pancreatic neuroendocrine tumor (50%)." (PMID 40920370, 2025). "Despite the fact that there is evidence connecting pancreatic NETs to VHL disease, neither a pathological analysis of several tumors nor a look at genetic alterations in VHL-associated NETs have been published." (PMID 37251595, 2023). "We found a case with authenticated VHL mutation p.Arg167Gln is not only associated with bilateral PPGLs but lung carcinoid and neuroendocrine tumor of pancreas, which have not been previously reported." (PMID 34923986, 2021). "In the majority of cases, VHL-associated pancreatic NETs are also non-functional, asymptomatic and typically slow growing." (PMID 24959293, 2014). "Therefore, in patients with VHL, the pancreatic NETs must be treated based on tumor size." (PMID 24959293, 2014).
pancreatic neuroendocrine tumor (continued). "In this cohort of patients, the sensitivities and specificities of VHL and MEN1/LOH alterations were 71% and 100% for SCNs and 68% and 98% for pancreatic neuroendocrine tumors, respectively." (PMID 36832193, 2023). "Pancreatic NETs (PanNETs) have been among the most studied, and research so far has outlined a series of recurring features, as inactivation of MEN1, VHL, TSC1/2 genes and hyperactivation of the PI3K/mTOR pathway." (PMID 29321190, 2018). "His 35 year-old daughter had 3 types of VHL-related tumors: Cerebellar hemangioblastoma, RCC in the right kidney lower pole, and pancreatic NET which invaded the superior mesenteric artery and superior mesenteric vein." (PMID 27439424, 2016). "Since the study also included patients with VHL-associated RCC and other VHL-associated tumors, responses were also observed in non-RCC lesions, including pancreatic neuroendocrine tumors (ORR 91%) and central nervous system hemangioblastomas (ORR 30%)." (PMID 38339352, 2024). "It is noteworthy that the HIF-2α inhibitor belzutifan represents a novel promising non-interventional option for inherited VHL-related pancreatic NETs, and has already been FDA-approved for renal cell carcinoma." (PMID 39456803, 2024). "In patients without VHL, pancreatic NETs should be treated according to the degree of differentiation and malignancy." (PMID 24959293, 2014). "Pancreatic cysts, serous cystadenomas and the more serious pancreatic neuroendocrine tumors but not PDAC arise in patients with VHL." (PMID 22873581, 2012). "In this context, individuals with non-hereditary (sporadic) pancreatic NETs may display functionally relevant VHL inactivation (haploinsufficiency or other kinds of epigenetic inactivation)." (PMID 33066332, 2020). "Since VHL neuroendocrine tumors are highly vascularized, it is possible that these islets lacking pVHL might be progressing toward developing pancreatic neuroendocrine tumors." (PMID 19340311, 2009).
erythrocytosis (38 papers, 2008 to 2025). "A total of five cases of hematopoietic disorders were also documented: monoclonal gammopathy, congenital erythrocytosis under phlebotomy therapy due to VHL mutation, favism, iron-deficiency microcytic anemia under iron therapy, and bone marrow dysplasia." (PMID 39685032, 2024). "An additional deep intronic homozygous variant in VHL, c.340 + 816A > C, was identified in another patient with congenital erythrocytosis, which was also confirmed to be pathogenic (Betty Gardie, personal communication)." (PMID 37946251, 2023). "So far, polycythemia has been recapitulated in transgenic mice with either VHL loss or EPAS1 gain-of-function mutation." (PMID 36040300, 2022). "Chuvash polycythemia, a secondary congenital erythrocytosis, was the first congenital erythrocytosis linked to a VHL mutation." (PMID 35205407, 2022). "Accordingly, it is revealed that the multi-organ hemangioblastoma and polycythemia in the proband are caused by VHL c.208G > A." (PMID 36384467, 2022). "The first mutation in VHL was found to be linked to erythrocytosis in the Chuvash region of Russia where there were a large number of cases of erythrocytosis." (PMID 34440325, 2021). "Four types of erythrocytosis are known to be caused by mutations in genes encoding key players of oxygen-sensing signaling, namely VHL (ECYT2), EGLN1/PHD2 (ECYT3), EPAS1/HIF2α (ECYT4) and EPO (ECYT5)." (PMID 34440324, 2021). "A number of other VHL mutations have identified as being associated with erythrocytosis, including other homozygote lesions and compound heterozygotes (listed in the work of Bento, 2014)." (PMID 34440325, 2021). "Between 2017 and 2021, the possibility of congenital erythrocytosis arose in 84 cases, so we performed a VHL mutation test as well, including rs779805." (PMID 34899081, 2021). "Urrutia and colleagues showed that pericyte specific (NG2:cre) VHL or PHD2/PHD3 deficiency leads to polycythemia." (PMID 33143240, 2020). "In line with this, polycythemia is one of the initial traits recognized in pheochromocytoma (the tumor of the adrenal medulla) relate to VHL or loss-of-function mutations or HIF2 gain-of-function mutations." (PMID 33143240, 2020). "The Chuvash population of the Russian Federation is associated with a high prevalence of polycythemia due to VHL gene mutation that reduces oxygen dependent HIF-2α degradation and increases EPO production." (PMID 32038269, 2019). "Until recently, Chuvash polycythemia, caused by germline R200W homozygous mutations in the von Hippel-Lindau (VHL) gene, was the only known form of congenital polycythemia to occur due to upregulation of the hypoxia signaling pathway." (PMID 29534684, 2018). "VHL single nucleotide polymorphism (rs779805)-associated polycythemia was also observed in a cohort of Hungarian patients followed up for polyglobulia of unknown cause." (PMID 40130200, 2025). "Recent research has demonstrated that splicing dysregulation in the E1’ and E2 regions of the VHL gene, leading to the formation of hypomorphic VHL variants, could be the underlying cause of erythrocytosis." (PMID 40647474, 2025). "However, to develop polycythemia associated with VHL disease Type 3, an individual must inherit two mutated VHL alleles, meaning it is an autosomal-recessive disease." (PMID 36040300, 2022). "Other VHL missense mutations lead to pulmonary hypertension and polycythemia." (PMID 34899081, 2021). "However, we found heterozygous (GA) or homozygous (AA) rs779805 VHL c.-195G>A polymorphism accompanied by erythrocytosis." (PMID 34899081, 2021).
erythrocytosis (continued). "Indeed, homozygosity for the VHL allele harboring the mutation R200W, which degrades HIFα subunits less efficiently than the WT VHL, is associated with HIF2α-dependent polycythemia and PH." (PMID 29882755, 2018). "A synonymous homozygous p.D143D change in patients with erythrocytosis was associated with exon 2 skipping, resulting in elevated levels of transcripts containing only exons 1 and 3; however, western blot analysis showed that all VHL isoforms were downregulated." (PMID 35205407, 2022). "CP is characterized by congenital erythrocytosis, and patients have been associated with pulmonary hypertension, thrombosis, vertebral hemangiomas, cerebral vascular events and other vascular abnormalities, displaying the role of VHL in HIF-dependent regulation of vasculogenesis and erythropoiesis." (PMID 33477877, 2021). "Variants of VHL found in Tibetans assist in optimizing the hypoxia response by managing HIF levels, reducing the risk of erythrocytosis, a common altitude-related disorder." (PMID 39600785, 2024). "While pVHL induced polycythemia is generally inherited in an autosomal-recessive manner, a study investigating eight children with polycythemia revealed one case in which a family harbored a heterozygous VHL mutant inducing a phenotype." (PMID 36040300, 2022). "Up to 50% of patients with apparent congenital erythrocytosis and elevated serum EPO appear to have a mutation in the VHL gene." (PMID 35205407, 2022). "The complex pattern of VHL splicing in the milieu of genetic changes in VHL exon and intron regions has been previously demonstrated in patients with VHL disease and erythrocytosis." (PMID 35205407, 2022). "Physiological studies on VHL and HIF2 mutated patients showed that, in Chuvash, polycythemia was highly characteristic of acclimatization to the hypoxia of high altitude and HIF2 mutations were associated with pulmonary hypertension." (PMID 34440325, 2021). "The homozygous VHL mutation R200W, which prevents efficient HIF-α degradation in normoxia, is found in all individuals with Chuvash Polycythemia (CP)." (PMID 33477877, 2021). "Erythrocytosis or erythrocytosis requiring phlebotomy were more common in patients with GA or AA genotype of VHL rs779805 SNP." (PMID 34899081, 2021). "We recommend VHL gene sequencing in young patients with otherwise unexplained (isolated) polycythemia, especially if there is any sign of familiarity or unusual precipitation of cancer in the family." (PMID 34899081, 2021). "We eagerly screened the VHL in young patients or evidence of a familiar polycythemia pattern or more cancer." (PMID 34899081, 2021). "Erythrocytosis and erythrocytosis requiring phlebotomy were more common in patients with VHL rs779805 GA or AA genotypes than the GG genotype." (PMID 34899081, 2021). "Except for VHL and BPGM-associated erythrocytosis, all other familial types have shown an autosomal-dominant type of inheritance." (PMID 34349782, 2021). "The central role of this pathway in regulating erythropoiesis was further underscored by the identification of patients with erythrocytosis that have mutations in PHD2 and HIF2α and the demonstration that Chuvash Polycythemia was caused by mutations in VHL." (PMID 20585586, 2010). "Patients homozygous for the Arg200Trp (R200W) VHL mutation, located in the extreme C-terminal domain of the 213 amino acid VHL protein (pVHL), develop Chuvash Polycythemia." (PMID 19030229, 2008). "Furthermore, the synonymous VHL:c.429C>T (p.Asp143=) variant has been reported in homozygous or compound heterozygous states in erythrocytosis patients, and has been characterized to induce exon 2 skipping, resulting in decreased VHL expression." (PMID 40647474, 2025). "There have also been documented cases of pVHL mutant-induced polycythemia (Type 3 VHL disease)." (PMID 36040300, 2022).
erythrocytosis (continued). "This research indicates that idiopathic erythrocytosis could be explained in the background of common single genetic variations (SNVs), possibly in interaction with other SNVs in VHL or VHL binding partners." (PMID 35205407, 2022). "However, CA-HIF-1α induced by VHL deletion or PHD1/2/3 inactivation causes excessive bone formation and polycythemia as well as disrupts the integrity of the osteocyte/canalicular network." (PMID 35118061, 2021). "Patient characteristics with homozygous GG genotype of VHL rs779805 G/A SNP with erythrocytosis." (PMID 34899081, 2021). "Patient characteristics with erythrocytosis and GA genotype of VHL rs779805 SNP." (PMID 34899081, 2021). "We present a long-term survey of pediatric liver recipients, evaluating prevalence, outcome and the main potential causes of erythrocytosis, including a comprehensive mutational analysis of commonly related genes (mutations of HBB and HBA, JAK2, EPOR, VHL, EPAS1 and EGLN1)." (PMID 32546701, 2020). "There are numerous other possible etiologies for polycythemia, including mutations in PHD enzymes, VHL proteins, alterations in angiotensin II signaling, upregulation of insulin-like growth factor-1 signaling, and constitutive activation of the JAK/STAT pathway." (PMID 32235007, 2020). "Mutations in VHL, PHD2, and HIF-2α have been identified in patients with familial erythrocytosis." (PMID 32038269, 2019). "Intriguingly, mutations associated to non-canonical VHL manifestations, such as polycythemia (14.8%), colorectal cancer (14.8%) and glial tumor (7.4%) seem mostly to derive from mutations of this interface." (PMID 30943211, 2019). "This type, which is caused by VHL gene inactivation at a specific point of the VHL protein, does not result in a tumor, it does, however, lead to polycythemia." (PMID 23843833, 2012). "To discover genetic variants in unexplained erythrocytosis, we performed whole exome sequencing in 27 patients with JAK2-negative polycythemia after excluding the presence of any mutations in genes previously associated with erythrocytosis (EPOR, VHL, PHD2, EPAS1, HBA, and HBB)." (PMID 37428608, 2023). "This discovery could be significant for certain pathologies where the erythropoietic effect is not desirable, such as secondary congenital erythrocytosis where disease develops due to mutations in genes regulating Epo such as VHL, EGLN1, EPAS1, or EPO." (PMID 35682566, 2022). "Interestingly, however, despite the fact that elevated HIFs in the background of certain VHL mutations has been associated with erythrocytosis, this condition is not a common feature of VHL disease." (PMID 35205407, 2022). "Germline and somatic mutations in genes involved in the hypoxia-sensing pathway, including Von Hippel-Lindau (VHL) and Egl-9 homolog 1 (EGLN1; also known as prolyl hydroxylase domain-containing protein 2 [PHD2]), have been described in neuroendocrine tumor syndromes associated with polycythemia." (PMID 32235007, 2020). "Constitutive activation of HIF-1α via VHL deletion or the combined inactivation of PHD1, PHD2, and PHD3 leads to polycythemia and excessive bone accumulation." (PMID 35118061, 2021). "Rankin and colleagues showed that specific deletion of VHL in osteoprogenitors in mice (OSX:cre-VHLf/f) presented elevated EPO expression in bone, which was also accompanied by polycythemia." (PMID 33143240, 2020). "In genetically modified mice, targeted deletion of VHL in osteoblasts over-stabilizes the hypoxic response and gives rise to high EPO production in osteoblasts that leads to severe polycythemia." (PMID 32038269, 2019).
erythrocytosis (continued). "The alteration of the VHL tumor suppressor gene results in the stabilization of hypoxia-induced factor 1/2α, which then increases the biosynthesis of erythropoietin (EPO), and thus leads to polycythemia." (PMID 38610939, 2024). "In patients diagnosed with PHEO/PGL and polycythemia with negative genetic testing for mutations in HIF2A, PHD1/2, and VHL, IRP1 should be considered as a candidate gene." (PMID 29534684, 2018). "Some rare cases of mutated VHL might induce isolated polycythemia; interestingly, the other tumors are mostly missing in these cases, so it is recommended to check the VHL in polycythemia if etiology is not otherwise explained." (PMID 34899081, 2021).